TNFRSF1A (TNF receptor superfamily member 1A)
Description:
Receptor for TNFSF2/TNF and homotrimeric TNFSF1/lymphotoxin-alpha. The adapter molecule FADD recruits caspase-8 to the activated receptor. The resulting death-inducing signaling complex (DISC) performs caspase-8 proteolytic activation which initiates the subsequent cascade of caspases (aspartate-specific cysteine proteases) mediating apoptosis. Contributes to the induction of non-cytocidal TNF effects including anti-viral state and activation of the acid sphingomyelinase.
Synonyms: CD120a; TNFAR; TNFR1; TNF-R; TNFR60; TNF-R-I; TNF-R55; FPF; TBP1; TNFR55; p55; p55-R; p60
Tractability: Small molecule: a structure with a bound ligand is known; it belongs to a druggable protein family. Antibody: a drug acting on it is in phase 1 trials; UniProt places it where antibodies can reach, with high confidence; its Gene Ontology location is reachable by antibodies, with high confidence; UniProt predicts a signal peptide or a membrane-spanning region. PROTAC: ubiquitination databases record sites on it; a small molecule that binds it is known.
Target class: Membrane receptor
Safety:
Unwanted effects reported when the protein is acted on. In parentheses: how it was acted on, where the effect was seen, and who reports it.
decreased blood pressure (activation, acute dosing; immune; source: Lynch et al. (2017))
decreased pain (inhibition, acute dosing; immune; source: Lynch et al. (2017))
increased pain (activation, acute dosing; immune; source: Lynch et al. (2017))
inflammation (activation, acute dosing; immune; source: Lynch et al. (2017))
lupus-like syndrome (inhibition, acute dosing; immune; source: Lynch et al. (2017))
sarcoidosis (inhibition, acute dosing; immune; source: Lynch et al. (2017))
Gene: Protein-coding gene on chromosome 12 (6,328,757 to 6,342,114, reverse strand). Ensembl gene ENSG00000067182.
Subcellular location: Cell membrane; Golgi apparatus membrane; Secreted; Secreted (Isoform 4)
Pathways (Reactome):
Signal Transduction: Regulation of TNFR1 signaling; TNF signaling; TNFR1-induced NF-kappa-B signaling pathway; TNFR1-induced proapoptotic signaling; TNFR1-mediated ceramide production
Immune System: Interleukin-10 signaling; TNFs bind their physiological receptors
Gene Ontology:
Molecular function: protein binding; tumor necrosis factor binding; signaling receptor activity; tumor necrosis factor receptor activity
Biological process: cell surface receptor signaling pathway via JAK-STAT; cellular response to mechanical stimulus; negative regulation of inflammatory response; positive regulation of canonical NF-kappaB signal transduction; positive regulation of transcription by RNA polymerase II; protein localization to plasma membrane; regulation of establishment of endothelial barrier; tumor necrosis factor-mediated signaling pathway; activation of NF-kappaB-inducing kinase activity; aortic valve development; cytokine-mediated signaling pathway; extrinsic apoptotic signaling pathway via death domain receptors; inflammatory response; negative regulation of extracellular matrix constituent secretion; positive regulation of apoptotic process involved in morphogenesis; positive regulation of inflammatory response; pulmonary valve development; apoptotic process; astrocyte activation; cellular response to lipopolysaccharide; establishment of blood-brain barrier; gene expression; negative regulation of cardiac muscle hypertrophy; positive regulation of execution phase of apoptosis; prostaglandin metabolic process; and 4 more
Cellular component: extracellular region; Golgi membrane; membrane raft; plasma membrane; receptor complex; tumor necrosis factor receptor superfamily complex; membrane; cell surface
Genetic constraint (gnomAD): Loss-of-function variants: 9 observed, 41.14 expected, observed/expected ratio (o/e) 0.22, 90% interval 0.13 to 0.38. The upper end of that interval is the gene's LOEUF score, 0.38, which puts it in group 1 of 6, group 1 being the genes least tolerant of losing a copy. Missense variants: 463 observed, 561.18 expected, observed/expected ratio (o/e) 0.83, 90% interval 0.76 to 0.89. Synonymous variants: 254 observed, 227.68 expected, observed/expected ratio (o/e) 1.12, 90% interval 1.01 to 1.24.
Gene-disease validity (ClinGen):
ClinGen rates the evidence that TNFRSF1A causes each of these diseases.
TNF receptor 1-associated periodic fever syndrome (autosomal dominant): Definitive. A periodic fever syndrome, characterized by recurrent fever, arthralgia, myalgia and tender skin lesions lasting for 1 to 3 weeks, associated with skin, joint, ocular and serosal inflammation and complicated by secondary amyloidosis.
Homologues: Orthologues: chimpanzee TNFRSF1A (99% identical), macaque TNFRSF1A (96% identical), rabbit TNFRSF1A (70% identical), pig TNFRSF1A (69% identical), guinea pig TNFRSF1A (67% identical), mouse Tnfrsf1a (63% identical), rat Tnfrsf1a (63% identical), dog TNFRSF1A (59% identical), tropical clawed frog tnfrsf1a (31% identical), zebrafish si:ch211-112c15.8 (19% identical), zebrafish tnfrsf1a (19% identical), zebrafish fas (14% identical). Paralogues in human: TNFRSF25 (19% identical), TNFRSF1B (16% identical), NGFR (16% identical), TNFRSF21 (15% identical), TNFRSF8 (15% identical), LTBR (15% identical), TNFRSF10B (15% identical), TNFRSF11B (15% identical), TNFRSF10A (14% identical), TNFRSF11A (13% identical), CD40 (13% identical), FAS (12% identical), and 9 more.
Diseases named in the same sentence as TNFRSF1A in open-access papers:
TNFRSF1A is named in the same sentence as 508 diseases in open-access papers, as found by Europe PMC text mining. Sharing a sentence is not in itself a finding about the gene and the disease. The quoted sentences say what the papers report.
rheumatoid arthritis (58 papers, 2009 to 2026). A chronic, systemic autoimmune disorder characterized by inflammation in the synovial membranes and articular surfaces. "Several studies have proposed that genetic variation in TNFRSF1A and TNFRSF1B was associated with susceptibility to inflammatory and autoimmune diseases, such as tuberculosis, systemic lupus erythematosus, rheumatoid arthritis and Crohn's disease." (PMID 23029405, 2012). "Recent studies proposed that genetic variation in TNFRSF1A and TNFRSF1B was associated with susceptibility to inflammatory and autoimmune diseases, such as tuberculosis, systemic lupus erythematosus, rheumatoid arthritis and Crohn's disease." (PMID 23029405, 2012). "Indeed, through genome-wide association studies, a single nucleotide polymorphism (SNP) in the TNFRSF1A gene encoding TNFR1 was discovered to be associated with MS, but not with other autoimmune conditions such as rheumatoid arthritis, psoriasis and Crohn’s disease." (PMID 32528961, 2020).
autoimmune disease (57 papers, 2009 to 2025). A disorder resulting from loss of function or tissue destruction of an organ or multiple organs, arising from humoral or cellular immune responses of the individual to their own tissue constituents. "TNFRSF1A is linked to a range of diseases including lupus erythematosus, arthritis, RA, infection, multiple sclerosis, autoimmune diseases, inflammatory bowel diseases, ulcerative colitis, pneumonia, and ankylosing spondylitis." (PMID 40839671, 2025). "We found that candidate variants at several risk loci are methylation quantitative trait loci (mQTLs), including mQTLs for DENNDIB, PLCL2, IRF5 and TNFRSF1A, all genes that are implicated in risk for other autoimmune diseases." (PMID 26394269, 2015). "Indeed, genome-wide association studies identified a single nucleotide polymorphism (SNP) in the TNFRSF1A gene coding for TNFR1 that is associated with MS but not with other autoimmune diseases, where anti-TNF therapy is working." (PMID 34305946, 2021). "In particular, two polymorphisms of the TNFR1-encoding gene, TNFRSF1A, the rs1800693 with high frequency and the rs4149584 with low frequency, have been identified and associated with an increased risk for MS and not for other autoimmune disorders." (PMID 33066433, 2020).
diabetes (53 papers, 2007 to 2026). "This is further corroborated by the fact that increased levels of two of these proteins were previously found to increase risk of CKD or end-stage renal disease (ESRD) in prospective studies in persons with diabetes (TNF sR-I (TNFRSF1A), NBL1 (DAN)." (PMID 38801599, 2024). "Consequently, TNFRSF1A serves as a crucial biomarker for diabetes in conjunction with MAFLD and presents as a promising therapeutic target." (PMID 40918148, 2025). "In diabetes with MAFLD, TNFRSF1A activation induces NF-kappa B translocation, resulting in the production of pro-inflammatory factors like IL-6 and TNF-α, which exacerbate liver inflammation." (PMID 40918148, 2025).
breast cancer (50 papers, 1994 to 2026). A primary or metastatic malignant neoplasm involving the breast. "High expression of TNFRSF1A was demonstrated to be associated with STAT3 activation in breast cancer cells, where STAT3 is known as a critical factor in tumorigenesis." (PMID 36035315, 2022). "Our results suggest that rs1061622 and rs1061624 in TNFRSF1B may affect breast cancer risk, and SNPs in TNFRSF1A are associated with the clinical features of breast cancer." (PMID 25010932, 2014). "The SNPs in TNFRSF1A were associated with the clinicopathological features of breast cancer." (PMID 25010932, 2014). "We also observed the transcriptional repression of the TNFRSF1A gene in other breast cancer cell lines SK-BR-3 and MDA-MB-231 upon transient over-expression of ETV7." (PMID 37041130, 2023). "We performed gene expression analysis using the TCGA database and observed a decrease in TNFRSF1A levels in breast cancer tissues (BRCA dataset) compared to matched normal tissues." (PMID 37041130, 2023). "Using the Kaplan–Meier plotter tool (TCGA dataset), we analyzed the impact of TNFRSF1A expression in breast cancer patients and confirmed a significant correlation between lower TNFRSF1A levels and poor prognosis of breast cancer patients." (PMID 37041130, 2023). "Subsequently, we also analyzed the expression of TNFRSF1A in breast cancer patients compared to normal breast tissue." (PMID 37041130, 2023). "In comparison, we found that the tumor necrosis factor receptor superfamily member 1 A (TNFRSF1A), a receptor for the cytokine TNFa, which is linked to EMT and metastasis in breast cancer, was overexpressed in basal B cells." (PMID 38055067, 2023). "In the current case-control study, we determined the associations between potentially functional SNPs in the TNF-α, TNFRSF1A and TNFRSF1B genes and breast cancer susceptibility." (PMID 25010932, 2014). "Additionally, three candidate genes are associated with Breast cancer (DLL3, BRCA2, WNT2B), the mTOR signaling pathway (WNT2B, TELO2, TNFRSF1A), and Pathways in cancer (DLL3, BRCA2, WNT2B)." (PMID 40919429, 2025). "However, Stat3 gene targets elevated in the Fyn neurodegeneration model included tnfrsf1a; its human homolog (TNFRSF1A) encodes a receptor for TNF-α (also known as TNF) and is associated with activation of the NF-κB pathway in breast cancer." (PMID 39641161, 2024). "Furthermore, we expanded our analysis and studied the expression of TNFRSF1A in an additional private cohort of breast cancer patients." (PMID 37041130, 2023). "Furthermore, we demonstrated that the knock-down of ETV7 restored the expression of TNFRSF1A in several breast cancer-derived cellular models." (PMID 37041130, 2023). "Afterwards, we investigated whether the expression level of TNFRSF1A influences the survival of breast cancer patients." (PMID 37041130, 2023). "Furthermore, the expression of TNFRSF1A was significantly lower in all molecular types of breast cancer compared to normal tissue." (PMID 37041130, 2023). "Thus, we were intrigued to understand if ETV7 affects the expression of TNFRSF1A also in breast cancer patients." (PMID 37041130, 2023). "Furthermore, we were able to confirm the down-regulation of TNFRSF1A also in two other breast cancer-derived cell lines, SK-BR-3 and MDA-MB-231, upon the transient over-expression of ETV7." (PMID 37041130, 2023). "However, to our knowledge, there are no published studies regarding the relationship between potentially functional SNPs in the TNFRSF1A and TNFRSF1B genes and the susceptibility to breast cancer among Asian populations." (PMID 25010932, 2014). "Moreover, in breast cancer cell lines, blocking TNFRSF1A or TNFRSF1B with specific antibodies impairs tumor survival signaling and the biological function of TNF-α." (PMID 25010932, 2014).
breast cancer (continued). "To better understand the roles of single nucleotide polymorphisms (SNPs) in the TNF-α, TNFRSF1A and TNFRSF1B genes in the development of breast cancer, we explored the associations between SNPs in these three genes and breast cancer susceptibility in northeast Chinese Han women." (PMID 25010932, 2014). "However, we did not found any correlation between TNF-α or TNFRSF1A polymorphisms and breast cancer risk." (PMID 25010932, 2014). "We confirmed that in breast cancer cells over-expressing ETV7, the repression of TNFRSF1A decreased the activation of NF-κB both in the basal state and upon the stimulation with TNF-α." (PMID 37041130, 2023). "We provide novel information on the fact that Haliclona fascigera extract exhibits anticancer properties against breast cancer via the activation of BIRC5, AKT1, MAPK, and TNFRSF1A genes." (PMID 37687120, 2023). "In breast cancer, a study has shown the potential biomarker of recurrent readthrough fusion transcripts of SCNN1A-TNFRSF1A (TNF receptor superfamily member 1A) as targets for anticancer treatment." (PMID 36139696, 2022). "Two genes (DAXX, ADAM17) are involved in ovarian cancer and three genes (TNFRSF1A, TIMP4, COL1A2) are exclusive to breast cancer." (PMID 31205821, 2019). "Knowing that TNF-α activates NF-κB signaling by binding to the TNFR1 receptor, we hypothesized that the ETV7-mediated repression of TNFRSF1A modulates the transcriptional activity of NF-κB in MCF7 and T47D breast cancer cells." (PMID 37041130, 2023). "Interestingly, in a private cohort of breast cancer patients, with triple-negative breast cancer patients’ subgroup we demonstrated an inverse correlation between the expression of ETV7 and TNFRSF1A." (PMID 37041130, 2023). "Moreover, we verified lower TNFRSF1A expression levels in breast cancer patients compared to normal breast tissues (from TCGA and in another private cohort) and this reduced TNFRSF1A correlated with a worse prognosis, which demonstrate the potential translational relevance of our observations." (PMID 37041130, 2023). "However, in the breast cancer cells over-expressing ETV7, we could not observe this regulatory mechanism, even when STAT3 was activated by the treatment with IL-6, thus demonstrating that there is a putative competitive relationship between ETV7 and STAT3 in the regulation of the TNFRSF1A gene." (PMID 37041130, 2023).
multiple sclerosis (43 papers, 2010 to 2025). A progressive autoimmune disorder affecting the central nervous system resulting in demyelination. "Functional studies have shown that TNFRSF1A is the causal gene underlying a neighboring, independent multiple sclerosis association in the region, about 70 kb upstream from rs2364485." (PMID 37563310, 2023). "This multiple sclerosis risk locus contains two plausible causal genes (TNFRSF1A and LTBR) and two independent signals for multiple sclerosis risk (rs1800693 and rs2364485)." (PMID 37563310, 2023). "For example, Tnfrsf1a−/− decreased susceptibility to experimental autoimmune encephalomyelitis, consistent with our observation that the risk allele for multiple sclerosis in Treg cells leads to increased TNFRSF1A gene expression levels." (PMID 35591976, 2022). "Enhanced control of TNFRSF1A gene expression by piRNA is apparently associated with its high risk of involvement in neurodegenerative diseases including multiple sclerosis." (PMID 36615932, 2022). "In this study we found that the functional SNP rs1800693 in the TNFRSF1A gene, encoding tumour necrosis factor receptor superfamily member 1A,33,34 was strongly predictive of progression to clinically definite multiple sclerosis: those carrying the C allele had a nearly 6-fold higher risk." (PMID 35891671, 2022). "Some SNVs show significant association with differences in alternative splicing, which may be important for disease, as illustrated by a variant of TNFRSF1A associated with multiple sclerosis, which encodes a novel form of TNFR1 that can block tumor necrosis factor." (PMID 25473428, 2014). "TNFRSF1A was defined as a susceptibility gene in tumor necrosis factor receptor-associated periodic syndrome (TRAPS) and multiple sclerosis (MS), which also plays certain roles in apoptosis and inflammation." (PMID 36138892, 2022). "The SNP rs1800693 in TNFRSF1A was identified in MS patients and control subjects (International Multiple Sclerosis Genetics Consortium [IMSGC], 2011)." (PMID 34045940, 2021). "Neurological manifestations and the co-occurrence of multiple sclerosis (MS) have been reported in patients with autoinflammatory diseases (AID) and variants of the NLRP3-, MEFV-, or TNFRSF1A gene." (PMID 32563262, 2020). "Variants in TNFRSF1A and in the vicinity of IRF8 were confirmed to be associated in these independent cohorts, which supports the role of these loci in etiology of multiple sclerosis." (PMID 21552549, 2011). "Higher production of proinflammatory TNFα and susceptibility to multiple sclerosis is also associated with some genetic variants in the NF-κB signaling cascade, such as variants proximal to NFκB1 and in an intron of TNFRSF1A (TNFR1), which leads to higher NF-κB signaling after stimulation with TNFα." (PMID 33271810, 2020).
Arthritis (42 papers, 2005 to 2025). Inflammation of a joint. "The R92Q mutation in TNFRSF1A could be involved in RA, as was seen in 5.2% of 135 patients with early arthritis." (PMID 31824568, 2019).
COVID-19 (39 papers, 2020 to 2025). A disease caused by infection with severe acute respiratory syndrome coronavirus 2. "recently reported the significant independent association of soluble TNFRSF1A with mortality in patients hospitalized with COVID-19." (PMID 35501457, 2022). "The high expression levels of C1R, CCL2, and TNFRSF1A in coronavirus disease-COVID-19 pathway were significantly related to the low survival in GBM patients." (PMID 35726234, 2022). "Survival analyses revealed a significant correlation between high expression of C1R, CCL2, and TNFRSF1A in the coronavirus disease-COVID-19 pathway and the poor survival in GBM patients." (PMID 35726234, 2022). "In the lungs, COVID-19 causes lung dysfunction by regulating the expression of SRC, RHOA, CD40LG, CSF1, and TNFRSF1A." (PMID 34504502, 2021). "We believe that the C1R, CCL2, and TNFRSF1A genes in the coronavirus-COVID-19 pathway may be activated in GBM patients, making GBM patients more susceptible to novel coronavirus infection." (PMID 35726234, 2022). "For example, the TNF receptor superfamily member 1A (TNFRSF1A) hub-high traffic gene may be a biomarker of mortality in severe COVID-19 patients, as increased expression of this gene was significantly correlated with mortalities." (PMID 34975885, 2021). "Post-COVID-19 exhibited lower levels of serum IL-6 (p adj <0.01), whereas it showed higher serum IL-10, triglyceride, leptin, IgG, ACE activity, TNFRSF1A, and PGE2 (p adj <0.05) levels compared with controls." (PMID 37753077, 2023). "Here, we found that post-COVID-19 patients presented higher systemic levels of PGE2, TNFRSF-1a, and IFN-α concomitantly to lower IL-6 concentrations." (PMID 37753077, 2023). "We found that the high expression of C1R, CCL2, and TNFRSF1A genes was particularly associated with the low survival in GBM patients, while other 41 DEGs enriched in the pathway of coronavirus disease-COVID-19 were not significantly connected with the overall survival of GBM patients." (PMID 35726234, 2022).